RBBP6 (RB binding protein 6, ubiquitin ligase)
Diseases named in the same sentence as RBBP6 in open-access papers (continued):
Sharing a sentence is not in itself a finding about the gene and the disease.
tumor (10 papers, 2012 to 2026). "In this study, we showed that RBBP6 is highly expressed in tumour-associated stroma, which was directly related to apoptosis levels and indirectly associated with Bcl-2 expression." (PMID 30886526, 2019). "We found that RBBP6 was overexpressed in colon tumorous tissues and was significantly associated with clinical stage, depth of tumor invasion, lymph node metastasis (LNM), distant metastasis, and histologic grade." (PMID 23799110, 2013). "Increased RBBP6 expression was significantly associated with depth of tumor invasion (pT stage, P = 0.005), LNM (pN stage, P = 0.002), distant metastasis (M stage, P<0.001), advanced AJCC (P<0.001) and differentiation (P = 0.007)." (PMID 23799110, 2013). "Furthermore, the overexpression of RBBP6 leads to cell cycle arrest, a common feature of tumorigenesis, and is strongly associated with tumor progression in cervical and esophageal cancer." (PMID 38667315, 2024). "Consistent with the in vivo screening results, RBBP6 KO inhibited tumor growth and prolonged survival of tumor-bearing mice." (PMID 38503731, 2024). "TCGA database and GEO database also showed RBBP6 levels were significantly upregulated in tumor tissues compared with normal tissues." (PMID 31685801, 2019). "Our results revealed a significant increase of RBBP6 in tumor tissues and the high expression of RBBP6 was closely related to poor survival of CRC patients." (PMID 31685801, 2019). "The result showed that the positive rate of protein RBBP6 was significantly different between the tumor tissues and the adjacent normal colon tissues." (PMID 31685801, 2019). "To investigate the role of RBBP6 in CRC progression, we first analyzed the expression levels of protein RBBP6 in normal colon mucosae and matched tumor tissues using a tissue microarray containing 180 pairs of samples." (PMID 31685801, 2019). "The results demonstrated that positive tumor RBBP6 expression was a significant independent prognostic factor for increased disease recurrence and decreased survival." (PMID 23799110, 2013). "Moreover, expression changes of epithelial and mesenchymal markers were also confirmed by western blotting and immunohistochemistry analysis performed with subcutaneous tumor tissues derived from nude mice, suggesting that RBBP6 enhances EMT in vivo." (PMID 31685801, 2019). "RBBP6 mRNA was expressed in the nuclei and cytoplasm of normal and tumour cervical epithelium." (PMID 30886526, 2019). "RBBP6 has been implicated in tumorigenesis but its role in tumor metastasis and progression has not been evaluated." (PMID 31685801, 2019). "RBBP6 expressed higher in the nodal metastasis than those in the primary tumor and normal tissue." (PMID 23799110, 2013). "CYLD (the familial cylindromatosis tumor suppressor gene) enhances the activation of the transcription factor NFkapa-B, RBBP6, (which binds to the retinoblastoma gene product pRB), and PNUTL2 (which is an apoptosis-related protein in the TGF-beta signaling pathway)." (PMID 23056957, 2012). "As CPSF3 appears to be a critical downstream molecule of RBBP6 in GSCs, we investigated the function of CPSF3 in tumor growth in vivo." (PMID 38503731, 2024). "To overcome this limitation, we performed parallel in vivo and in vitro CRISPR/Cas9 functional screens to investigate targetable dependencies of GSCs and identified RBBP6 as a consistent regulator of GSC maintenance and tumor formation in vitro and in vivo." (PMID 38503731, 2024). "Depletion of RBBP6 or CPSF3 resulted in 3’US of the ceRNA of the OG MYC, thereby reducing MYC expression and leading to inhibition of tumor growth." (PMID 38503731, 2024). "RBBP6 promoted cell proliferation, migration, and invasion in CRC cells and promoted tumor growth, lung metastasis, and liver metastasis in mouse models." (PMID 31685801, 2019). "The data indicated that RBBP6 expression was positively correlated with CRC development, neoplasm metastasis, and NF-κB-signaling gene signatures." (PMID 31685801, 2019).
tumor (continued). "Targeting RBBP6 inhibited GSC proliferation and tumor initiation." (PMID 38503731, 2024). "In view of the fact that EMT is a critical event in tumor invasion and metastasis, we assessed whether EMT was responsible for RBBP6-mediated changes in CRC cell motility." (PMID 31685801, 2019). "RBBP6 KO induced apoptosis, as measured by annexin V staining and PARP cleavage in GSCs but not non-stem tumor cells (NSTCs) and iPSC-induced astrocytes and neural progenitor cells (NPCs)." (PMID 38503731, 2024).
infection (3 papers, 2015 to 2025). The state of being infected such as from the introduction of a foreign agent such as serum, vaccine, antigenic substance or organism. "To validate this interaction during infection, we performed endogenous RBBP6 immunoprecipitation (IP) in YFV-17D-infected Huh7 cells." (PMID 40631121, 2025). "Several infection-induced SUMO targets also are involved in mRNA maturation events, such as 3′ end pre-mRNA processing (CPSF1, CPSF2, FIP1L1, RBBP6, and WDR33), splicing (CLASRP, SFPQ, and ZRANB2), and nuclear RNA quality control (ZC3H18, ZCCHC7, and PAPD5)." (PMID 26549460, 2015).
RBBP6 also shares sentences with these, for which no sentence is quoted: adenocarcinoma (1 paper); atrial fibrillation (1); cancers of the pancreas (1); chondrosarcoma (1); colon (1); Fanconi anemia (1); Hearing impairment (1); invasive carcinoma (1); liver cancer (1); lung (1); melanoma (1); Stroke (1).